TLR7 (toll like receptor 7)
Diseases named in the same sentence as TLR7 in open-access papers (continued):
Sharing a sentence is not in itself a finding about the gene and the disease.
tumor (continued). "TLR7 and TLR9 agonists have been used to activate tumor-associated pDCs and showed some clinical benefit." (PMID 35311157, 2022). "In the preclinical studies, researchers mainly focused on the delivery efficiency of TLR agonists into the tumor site; intratumoral injection or nanoparticle-conjugate of TLR7/8 agonists were widely studied to overcome lowering the local drug dose in tumors." (PMID 35292881, 2022). "As innate immunotherapeutic agents, TLR7/8 agonists have the potential to induce immuno-regulation function, which is supposed to bridge the innate cellular immune to tumor immunotherapy." (PMID 36476317, 2022). "The TLR7 agonist 852A phase-II study revealed anti-tumor activities in patients with breast, ovarian, endometrial, and cervical cancers." (PMID 36476317, 2022). "Nanoparticle complexes comprising TLR3 and TLR7 agonists poly(I:C) and imiquimod, respectively, were demonstrated to achieve complete tumor rejection in a B16 melanoma model." (PMID 35740589, 2022). "For example, studies have shown that TLR7/8-agonist-loaded nanoparticles can promote the M2 to M1 type switch of macrophages, leading to controlled tumor growth." (PMID 36186906, 2022). "Our group has been committed to the development of small-molecule TLR7 (Toll-like receptor 7) agonists, which have been widely investigated in the field of tumor immunotherapy." (PMID 36499455, 2022). "Smac-TLR7/8 hydrogel with radiation displayed the highest tumor inhibition rate (86.3%), owing to the synergistic effect of combination radioimmunotherapy." (PMID 36145656, 2022). "KEGG signaling pathway analysis suggested that TLR7 was involved in dendritic cell developmental lineage pathways and in the interaction between immune cells and microRNAs in the tumor microenvironment." (PMID 36329841, 2022). "TLR7 has been reported to induce cell survival and tumor growth, most likely via NF-κB activation and upregulation of Bcl-2." (PMID 35742983, 2022). "TLR7 agonists delivered into the tumor microenvironment can then further diffuse into bystander cells, thus causing a proinflammatory field effect." (PMID 35806163, 2022). "TLR7 not only played an immunosurveillance role on activation of innate and adaptive immune effectors, but also exhibited a dual regulatory effect on tumor progression." (PMID 35413927, 2022). "Combination of TransCon TLR7/8 Agonist with systemic immunotherapy further promoted anti-tumor activity in TransCon TLR7/8 Agonist-treated tumors." (PMID 36123697, 2022). "For example, TLR7/8 agonists can directly inhibit IL17 signaling in Th17 cells which can contribute directly to tumor growth inhibition." (PMID 36551577, 2022). "Consistently, when TransCon TLR7/8 Agonist was injected intratumorally in CT26 tumor bearing mice, a similar low but long-term and dose-proportional systemic drug exposure was observed, suggesting that the TME did not affect the release rate of resiquimod." (PMID 36123697, 2022). "Both CD40-positive and CD40-negative B cells were isolated from tumors of TLR-7/8 agonist-treated wild-type mice and adoptively transferred into tumor-bearing B cell KO mice, which were treated with anti-PD-L1 and TLR-7/8 agonist." (PMID 35720386, 2022). "TLR7 agonists R837 in combination with γ-ionizing radiation (IR) reduced tumor growth through autophagy, with elevated CD8+ T cells and decreased Tregs and MDSCs in tumor lesions." (PMID 35745800, 2022). "We combined trastuzumab X-body with TLR7/8 agonist, the combination therapy improved tumor inhibition activity and produced 6 days and 9 days tumor growth delay compared to X-body and R848 treatment alone." (PMID 36451853, 2022). "TLR7 plays a crucial role in activating both natural and acquired immune responses and has an activating effect on virtually all cells engaged in the tumor immune response." (PMID 35957907, 2022).
tumor (continued). "Despite inducing relatively low systemic cytokine and chemokine levels, a single IT administration of TransCon TLR7/8 Agonist induced robust chemokine and cytokine protein expression in the tumor." (PMID 36123697, 2022). "Once activated via TLR7/9, pDCs directly participate in the anti-tumor immune response through antigen presentation, although with a weaker capability than cDC subsets." (PMID 36230990, 2022). "In this study, we construct a novel tumor vaccine (SZU251 + MUC1 + Al) with three components: a small-molecule TLR7 agonist synthesized for the first time (SZU251), an MUC1-related peptide (MUC1), and an aluminum adjuvant (Al)." (PMID 36499455, 2022). "Although many studies have demonstrated that TLR7 agonists can enhance anti-tumor immune responses, these agonists also stimulate TLR7-expressing tumor cells." (PMID 36476317, 2022). "For example, one study showed TLR7 stimulation induced tumor cell survival and resistance to chemotherapy." (PMID 36476317, 2022). "Following dosing, soluble resiquimod did not provide significant anti-tumor activity; conversely, TransCon TLR7/8 Agonist demonstrated potent and sustained anti-tumor benefit." (PMID 36123697, 2022). "Recently, small-molecule TLR7 agonists have been widely investigated in the field of tumor immunotherapy through inducing tumor-specific immune responses and reducing the tumor growth." (PMID 36499455, 2022). "The covalent attachment of TLR7 agonists to the surfaces of tumor cells enhanced dendritic cell (DC) activation to induce the more specific recognition of tumor cells." (PMID 35805071, 2022). "In a mouse tumor model, NK cells activated at a distant site by a TLR7/8 agonist released tumor antigens and induced tumor-specific CD4+ T cells." (PMID 35768424, 2022). "Treatment with free TLR7/8 and irradiated Smac hydrogel resulted in 11.0 and 57.2% suppression of the tumor growth rate, respectively." (PMID 36145656, 2022). "Further, a folate-conjugated TLR7 agonist showed in vivo activity in assorted tumor models and reversed expression of a high M2-like to M1-like macrophage ratio and increased the infiltration of cytotoxic CD8 T cells." (PMID 35790779, 2022). "B16 tumor-bearing B cell KO and WT mice were treated intratumorally with TLR-7/8 agonist or vehicle; serum was collected at various time points and analyzed for the presence of B16 tumor-specific serum IgG antibodies by ELISA as described under methods." (PMID 35720386, 2022). "Immune adjuvant R848 is an agonist of TLR7/8, inducing antitumor immune responses against tumor malignancies." (PMID 36145656, 2022). "DSR-29133, a potent selective TLR7 agonist, can induce anti-tumor immune responses that can be further enhanced through combination with low-dose fractionated radiotherapy in different murine solid tumor models, including CRC (CT26)." (PMID 36476317, 2022). "The polymer is endowed with TLR7 agonizing moietiesand with mannose moieties to mark tumor debris for APC endocytosisand to further localize the TLR7 agonist within the endosome, thecompartment in which the receptor is active." (PMID 36313164, 2022). "Another in situ anti-tumor vaccination was a multifunctional nanocomplex based on calcium crosslinked polyaspartic acid conjugated to both TLR7/8 agonist IMDQ and the photosensitizer IR780." (PMID 35745800, 2022). "TLR7 is highly expressed in primary NSCLC tumor cells and affords resistance to chemotherapeutic agents." (PMID 36389785, 2022). "TLR7/8 are located in the intracellular endosomes, participate in tumor immune surveillance and play different roles in tumor growth." (PMID 36476317, 2022). "In an LLC tumor model carrying microRNA‐21, tumor‐derived exosomes stimulate apoptosis of myoblasts via TLR7 signaling and lead to muscle wasting." (PMID 36105371, 2022).
tumor (continued). "Following TransCon TLR7/8 Agonist administration, significantly elevated proinflammatory cytokine and chemokine expression was detected in the tumor over 7 days, consistent with sustained release of resiquimod from TransCon TLR7/8 Agonist within the TME." (PMID 36123697, 2022). "The combination of imiquimod, a TLR7 agonist, and GM-CSF gene-transduced tumor vaccines activates pDCs and enhances their immunologic antitumor effects." (PMID 35311157, 2022). "R848, particularly when combined with anti-CD200R, improves the antitumor effects of TLR7 signaling and the local tumor microenvironment by altering the phenotype of intratumoral myeloid cells." (PMID 36476317, 2022). "On the other hand, some TLRs seem to play a dual role in promoting or suppressing tumor progression depending on the type of cancer; for example, TLR7/8 has been reported to mediate anti-tumor effects due to their role on DC and NK cell activation." (PMID 35742983, 2022). "TLR7/8 agonist imiquimod was proven to activate NK cells to kill tumor cells and induct tumor-specific CD4+ T cells, resulting in a strong regression of low MHC-I tumors." (PMID 35413927, 2022). "One method for converting TAMs and MDSCs to a more tumor-suppressing (M1-like) phenotype has been to treat the myeloid cells with a TLR7 agonist." (PMID 35250995, 2022). "Lnc‐FMR1‐AS1 can be packaged into exosomes and released into the tumour microenvironment, and maintain the dynamic interconversion state of tumour stem cells by activating TLR7‐NFκB signalling and up‐regulating c‐Myc levels in recipient cells." (PMID 34981655, 2022). "The released immunogenic factors and the precise activation of the tumor TLR7 pathway trigger adaptive anti-tumor responses through an in situ vaccine-like function." (PMID 35832074, 2022). "We have constructed several tumor vaccines by conjugating TLR7 agonists and TAAs and have proven the antitumor effects of the vaccines in previous studies." (PMID 36499455, 2022). "TLR4 and TLR7 were the most strongly correlated with tumour stemness features, but TLR9 had an undefined connection with the stemness index in various malignancies, and TLR4, TLR7, and TLR8 were the most associated with the tumour microenvironment." (PMID 35801728, 2022). "The results showed that the expression of CD2, SPN, IL18, PTPRC, GZMA, and TLR7 was upregulated in the tumor group compared with the normal group (p < 0.05)." (PMID 36591509, 2022). "On the one hand, TLR7 activation recruited immunosuppressive cells to facilitate tumor-immune escape." (PMID 35413927, 2022). "TLR7 activation of tumor cell lines such as Hela S3, keratinocytes, and fibroblasts directly promoted tumor cell apoptosis." (PMID 34124272, 2021). "Significant down-regulations of TLR2 and TLR7 mRNA were found in both peripheral and tumor-infiltrating CD8+ T cells from GC patients." (PMID 34620075, 2021). "A number of other studies, however, have reported synergy between TLR7/8 agonists and checkpoint inhibitors in various other murine tumor models." (PMID 34058283, 2021). "In recent years, TLR7 has been intensively studied in virus‐induced immune cell activation and tumor immunity." (PMID 33463061, 2021). "TLR7/8 agonists are showing promising preclinical results in overcoming tumor resistance to checkpoint blockade." (PMID 34058283, 2021). "TLR7 is a member of the Toll-like receptor family and plays a key role in the proliferation of tumor cells." (PMID 34026613, 2021). "To obtain a first hint of the bidirectional cytotoxic activity of HDACis and TLR7/8as in OC cell lines and primary tumour cells, we performed an isobolographic analysis which combined the two drug classes." (PMID 33658617, 2021). "It has been reported that TLR7/8 therapy leads to the expansion of tumor antigen-specific CD8+ T cells, which is important for the development of an effective antitumor immune response." (PMID 33790276, 2021).
tumor (continued). "Antigen presentation was markedly improved when the tumor antigen liposomes were co-formulated with the TLR7/8 agonist TMX-201." (PMID 34611284, 2021). "In order to understand the effect of NK cells pretreated with TLR7/8 agonists on tumor cells, we performed ADCC assays with the most promising compounds in the degranulation assay (522, 543, 574 and 558)." (PMID 33558639, 2021). "Each patient received at least two intratumoral quadrivalent HPV-L1 vaccine (GardasilTM) injections and daily topical TLR-7 agonist (imiquimod) to the tumor surface 2 weeks apart." (PMID 34987310, 2021). "CO2 gas generated at acidic pH due to the sodium bicarbonate that was coloaded for better release and encapsulation of the TLR7/8 agonist 522, and the nanoparticles showed great tumour reduction." (PMID 34830392, 2021). "Other studies, however, show they can promote tumor growth in the lung; thus, the effects of TLR7/8 ligands on different types of tumor cells are cancer and tissue context-dependent." (PMID 34058283, 2021). "TLR7/TLR8 activation via TLR7/TLR8 agonist R848 induces M-MDSC differentiation into anti-tumor M1-type macrophages, whereas TLR1/TLR2 activation facilitates the M-MDSC transformation into suppressive M2-type macrophages." (PMID 34336860, 2021). "The provided TLR7/8 stimulation thereby ensures that pDCs are activated and supports CD8α+ cDC engagement for priming of tumor reactive CD8+ T cells." (PMID 34611284, 2021). "Ultimately, TLR7, which is significantly related to tumor progression and prognosis, emerged as the hub gene in STAD." (PMID 33982398, 2021). "Using topical TLR7 agonist imiquimod in patients with skin metastases from breast cancer showed 20% partial response with histologic tumor regression with changes in tumor lymphocytic infiltrate and local cytokines profile." (PMID 34771482, 2021). "In a breast cancer mouse model, delivery of this miRNA mimic led to a reversal of the tumor-suppressive properties of TAMs by acting as a TLR-7 agonist and suppressing IL-10 production, thereby inhibiting tumor growth." (PMID 33530393, 2021). "We also compared the mRNA levels of TLR7 between tumor and normal tissues using the Oncomine database." (PMID 33982398, 2021). "Research on TLR7 not only emphasizes its immunosurveillance role through the activation of innate and adaptive immune effectors, but also its promotion effect on tumor progression." (PMID 33982398, 2021). "TLR7/8 activation has been shown to differentiate MDSCs in the tumor microenvironment towards M1 phenotype and enhance tumor regression in mice." (PMID 34124272, 2021). "Recently, we showed that TLR7 stimulation changes the tumor microenvironment to become pro-inflammatory and less supportive for tumor growth while decreasing CD200R expression on myeloid cells." (PMID 34069671, 2021). "This antitumor TLR7 effect was also shown in CNS tumors which increased DC maturation and tumor-specific CD8+ T cells in mice." (PMID 34124272, 2021). "This enzyme-responsive activity represents another promising step toward synthetic TLR7/8 agonist-based formulations that can preferentially release active cargo based on specific cues in the tumor microenvironment." (PMID 34058283, 2021). "TLR7/8 activation is reported to induce an anti-tumor effect by the release of cytokines such as TNF-α and interleukin-12 and by activation of cytotoxic T lymphocytes." (PMID 32046113, 2020). "Treatment of p48-Cre:KRASG12D mice with a TLR7 agonist greatly accelerated stromal expansion and tumor progression." (PMID 32961746, 2020). "The TLR7 antagonist Loxoribin inhibited tumor growth in xenograft models of colon cancer and lung cancer by promoting CD4+ T cell proliferation, reversing CD4+CD25+ Treg-mediated suppression via DCs." (PMID 32746880, 2020).
tumor (continued). "Liposomes formulated by loading imiquimod R837, an immune adjuvant TLR7 agonist, and hematoporphyrin monomethyl ether, a sonosensitizer, showed promising tumor growth arrest and was also helpful in preventing metastasis to the lung." (PMID 32521684, 2020). "As observed with TLR9 agonists, attempts to improve the retention of TLR7/8 agonists in the tumour by formulating resiquimod into thermosensitive liposomes have been investigated." (PMID 33352882, 2020). "Activation of TLR7 and inhibition of TGF-β receptor I (TβRI) reprogrammed tumor-associated macrophages into M1-type macrophages." (PMID 33381518, 2020). "Once activated via TLR7/9L, pDCs potentially achieve tumor control through efficient priming of antitumor responses." (PMID 33282290, 2020). "Certain TLR7/8 agonists have been shown to promote anti-tumor immunity by enhancing the pro-inflammatory tumor micromilieu." (PMID 32183240, 2020). "In the present study, we synthesized a novel TLR7 agonist SZU-106 that is suitable to be conjugated to tumor cells." (PMID 32922200, 2020). "One strategy to induce T cells and overcome a “cold” tumor’s TME burden uses vaccines such as the FDA-approved Toll-like receptor 7 (TLR7) agonist imiquimod." (PMID 32509781, 2020). "On the other hand, other studies support activating TLR7/8 as a therapeutic strategy, mainly through promoting an immune-mediated anti-tumor response." (PMID 32961746, 2020). "In order to make it possible to conjugate the TLR7 agonist to tumor cells, we added a carboxyl group to SZU-101 and synthesized a new chemical SZU-106." (PMID 32922200, 2020). "By contrast, a TLR7/8 ligand (R848) can stimulate both pDCs and mDCs, and this approach will be more effective in eliciting an antitumor response at the tumor site." (PMID 32012718, 2020). "Next, we examined the changes of TLR7 activation and Pim-3-silencing-related apoptosis of tumor tissues after different treatment." (PMID 31849942, 2019). "Previously E-selectin negative tumor-associated vessels in human SCC samples up-regulated E-selectin following treatment with imiquimod (TLR-7 agonist) which resulted in CD8+ T cell influx into the tumor and tumor regression." (PMID 31231358, 2019). "In vivo, the supramolecular association limited systemic toxicity as compared to the unmodified TLR7/8 agonist while arresting tumor growth." (PMID 31879528, 2019). "We report here that the unique structure and formulation of MEDI9197 enables it to be retained within the tumor after IT delivery, minimising systemic drug exposure and cytokine release, and driving sustained local TLR7/8 activation in the TME." (PMID 31511088, 2019). "TLR7 agonists have long been utilized in pre-clinical studies as immune adjuvants that enhance anti-tumor and anti-viral immunity." (PMID 31998321, 2019). "The TLR7 agonist Imiquimod has been shown to enhance immune-mediated tumor regression in melanoma, basal cell carcinoma and breast cancer when applied as a topical cream (Aldara)." (PMID 30979057, 2019). "The activation of TLR3 and TLR7 triggers Th1 polarization in a tumor through increased IL-12, IL-23, and type I IFN production." (PMID 31083581, 2019). "Another group combined TLR7/8 ligand R848 with anti-PD-1 therapy in vivo to see inhibition of tumor growth even in PD-1 resistant mice." (PMID 31695691, 2019). "Tumor-infiltrating pDCs display an impaired response to TLR7/9 activation and decreased or defective production of type I IFN, and contribute to the establishment of an immunosuppressive tumor microenvironment through high expression of PD-L1 and IDO." (PMID 31849942, 2019). "TLR7-based adjuvants also enhance anti-tumor effector T cell activity and subvert immunosuppression mediated by regulatory T (Treg) cells and tumor-associated macrophages." (PMID 31507609, 2019).